IFNAR1 (interferon alpha and beta receptor subunit 1)
Diseases named in the same sentence as IFNAR1 in open-access papers (continued):
Sharing a sentence is not in itself a finding about the gene and the disease.
infection (continued). "The bacterial burden in the MLNs, liver, and spleen was significantly higher in WT than in Ifnar1-/- animals on days 3 and 5 after infection (respectively)." (PMID 29190678, 2017). "In the MBT liver, the increase was also weaker compared to the BALB/c liver, but by day 3 post infection IFNAR1-positive leukocyte levels surpassed levels found in BALB/c liver." (PMID 28769107, 2017). "Consistently, the difference in CFU between Ifnar1-/- and WT mice was increasing with time of infection." (PMID 29112952, 2017). "The majority of transcripts which were identified to be significantly differentially expressed in WT and Ifnar1-/- strains of mice were changed as a result of the infection at days 2 and 3 post-infection." (PMID 26918359, 2016). "Ifnar1-/- mice succumb to CW3 infection within seven days indicating that type I IFN responses are critical for control of CW3." (PMID 27327515, 2016). "Strikingly, an upregulation of a significant number of transcripts was observed at day 1 post infection in blood of the Ifnar1-/- as compared to WT mice, although there was not a significant change in the bacterial load at this time post infection." (PMID 26918359, 2016). "We next examined the impact of IFNAR1-signalling on parasite control and humoral immune responses during Py17XNL-infection." (PMID 27812214, 2016). "In contrast, a higher percentage of up-modulated genes was observed in the blood of infected WT mice as compared to the infected Ifnar1-/- mice at days 2 and 3 post infection (where the bacterial load was reduced in the Ifnar1-/- mice;)." (PMID 26918359, 2016). "A higher percentage of down-modulated genes was observed in the blood of infected WT mice as compared to the infected Ifnar1-/- mice at day 1 post infection (when the bacterial load was identical)." (PMID 26918359, 2016). "Following infection there was a greater relative percentage of pDC in both the blood and the spleen of the WT mice compared to the Ifnar1-/- mice." (PMID 26918359, 2016). "This identified the final net difference in the maximal gene expression change upon infection in the Ifnar1-/- as compared to the WT mice having taken into account the Ifnar1-/- baseline difference." (PMID 26918359, 2016). "In the spleen an increase in the proportion of pDC was observed in the WT and this was abrogated in the Ifnar1-/- upon infection." (PMID 26918359, 2016). "In contrast, B cell expression of MHC I and CD86 was unaltered at day 3 post infection in RRV-infected NOD.IFNAR1−/− mice." (PMID 27405244, 2016). "The IFN signaling pathway ranked as the top canonical pathway for all time points post infection, found to be differentially perturbed in the blood of infected WT as compared to infected Ifnar1-/- mice." (PMID 26918359, 2016). "Compared to infected WT controls, Ifnar1-/- mice displayed increased Tfh proportions and numbers during Py17XNL infection, and increased proportions during PcAS infection." (PMID 27812214, 2016). "We observed virtually identical fecal shedding of EW-RV in WT, Ifnlr1-/-, Ifnar1-/-, Ifnar1-/-Ifnlr1-/- or Stat1-/- mice during the first 7 days post infection (dpi)." (PMID 27128797, 2016). "It should be noted that there was perturbation of a larger number of transcripts at days 2 and 3 than day1 post-infection in blood and tissues of both Ifnar1-/- and WT mice." (PMID 26918359, 2016). "IFNAR1-signalling hindered the resolution of infection, and acted early via conventional dendritic cells to restrict CD4+ T-cell activation and their interactions with B-cells." (PMID 27812214, 2016). "This identified the final net difference in the maximal gene expression change upon infection in WT as compared to the Ifnar1-/-, having taken into account the WT baseline difference." (PMID 26918359, 2016).
infection (continued). "A smaller proportion of transcripts were significantly differentially expressed as a result of the combination of infection and WT and Ifnar1-/- mouse strains at days 2 and 3 post-infection, where there was a significant difference in bacterial loads." (PMID 26918359, 2016). "Expression of Irf7, which is known to be one of the most inducible Irf genes was induced in the Ifnar1-/- upon infection to an equivalent degree as compared to the WT." (PMID 26918359, 2016). "A key difference between Ccr2—/—and Ifnar1—/—mice, however, is that CCR2 deficiency is favourable for infection outcome whereas Ifnar1—/—deficiency leads to enhanced mortality compared to WT animals." (PMID 26731100, 2016). "In contrast at day 1 post-infection there were major changes in gene expression in blood and spleen observed as a result of strain plus infection (i.e. WT versus Ifnar1-/- mice, infected)." (PMID 26918359, 2016). "By comparing the fold change response of transcripts to infection in WT or Ifnar1-/- mouse strains, it was seen that the response was broadly comparable in the WT and Ifnar1-/- despite the absence of type I IFN signaling." (PMID 26918359, 2016). "It is also of note that pDC MHC I levels in MLN and PLN on days 3 to 14 after mock infection were higher in NOD than NOD.IFNAR1−/− mice." (PMID 27405244, 2016). "Their transcript level in the cecum was assessed in both WT and Ifnar1-/- mice at 8 dpi after PR8 or mock infection, and following a secondary S. Typhimurium infection." (PMID 27149619, 2016). "We observed increased expression of Stat1 in the blood of infected Ifnar1-/- mice versus WT controls at day 1 post infection when bacterial loads were similar, suggesting a direct of role of type I IFN signaling." (PMID 26918359, 2016). "Greater differences in gene expression as a result of L. monocytogenes infection were observed in both WT and Ifnar1-/- as compared to uninfected mice by day 2 post infection, and this increased at day 3 post infection." (PMID 26918359, 2016). "Two-days-old wild-type, Ifnlr1-/- and Ifnar1-/- animals were orally infected with reovirus, and viral titers in small intestine and colon were analyzed on day 4 post-infection." (PMID 25849543, 2015). "Accordingly, reovirus replication in the terminal small intestinal tissue at day 4 post-infection was significantly higher in Ifnar1-/- mice compared to Ifnlr1-/- or wild-type animals." (PMID 25849543, 2015). "The blockade of IFNAR1 resulted in increased viremia in the early phase of infection, but within 12 days the viral loads in the blood decreased to levels found in mice that had not received the blocking antibody." (PMID 26588782, 2015). "High levels of nuclear Mx1 were detectable in the majority of IECs in tissue samples from wild-type and Ifnar1-/- animals already at day 1 post-infection." (PMID 25849543, 2015). "Reovirus antigen was almost exclusively found in IECs of Ifnlr1-/- mice at day 4 post-infection, whereas reovirus was restricted to lamina propria cells in Ifnar1-/- mice." (PMID 25849543, 2015). "By day 4 post-infection, wild-type animals had largely cleared the virus, whereas the intestinal tissue of Ifnar1-/- and Ifnlr1-/- mice was still heavily positive for reovirus antigen." (PMID 25849543, 2015). "Conversely, neutralisation of the IFN-α/β receptor IFNAR1 by monoclonal antibodies during infection was able to rescue replication of FL-IRAΔCS3 mutant virus in wild-type MEFs." (PMID 24473339, 2014). "Taken together, our results supported the concept that continuous recruitment of CCR2+ inflammatory monocytes by the IFNAR1-triggered chemokine feedback loop is attributable to the extended duration of IFNβ expression in the late phase of infection." (PMID 25407417, 2014). "In contrast to the intranasal challenge, intraperitoneal (i.p.)infection of Ifnar1−/− and Ifnar1+/+ mice resulted in similar bacterial titers in the blood 12 hours post-infection." (PMID 24244159, 2013).
infection (continued). "This difference was maintained at 24 and 48 hours after infection, by which time 91% of the Ifnar1−/− mice were bacteremic compared to 36% of the Ifnar1+/+ mice." (PMID 24244159, 2013). "For these reasons, we sought to determine the basal level of different IFN-signalling intermediates at steady state and upon infection in IFNAR1−/−IL-28Rα−/− cells." (PMID 24278020, 2013). "We report severely reduced levels of inflammatory mediators and innate immune cells in blood and kidneys of Ifnar1−/− mice upon Ca infection, suggesting a pro-inflammatory role of IFNs-I in this infection model." (PMID 22911155, 2012). "Inspection of animals 2 days post challenge revealed that neutrophils were more abundant at the site of infection in the IFNAR1-/- mice indicating that type I IFNs negatively regulated neutrophil recruitment." (PMID 21625574, 2011). "Because we found 54Stop defective in inhibiting type I IFN signaling due to its inability to induce IFNAR1 degradation, we assayed the downstream induction of ISGs following infection of bone marrow derived macrophages." (PMID 21998588, 2011). "We observed that the infection of KR-2 cells with HSV stimulates degron phosphorylation of endogenous human IFNAR1 and robustly downregulates the levels of this receptor." (PMID 21695243, 2011). "Infections of Ifnar1−/− mice with rZHΔNSs or with Clone 13 gave similar results (and data not shown)." (PMID 22163058, 2011). "The Ifnar1−/− mice started to die 5 days post infection (dpi) and all were dead within 8 dpi while approximately 50% of WT mice survived." (PMID 21383977, 2011). "Both A549 and Vero cells had lower surface expression of IFNAR1 following hMPV infection, while the total cellular abundance of IFNAR1 was comparable in mock- and hMPV-infected cells." (PMID 21949722, 2011). "Future studies in vivo aimed at a further delineation of the mechanisms of IFNAR1 degradation and its role in sensitivity to secondary infections and autoimmune disorders are consequently warranted." (PMID 21695243, 2011). "In 129 WT, IFNAR1−/− and IFNGR−/− mice, clinical findings including weight loss data and morbidity were identical after infection with rMA15." (PMID 20386712, 2010). "By day 5 post-infection, viral RNA was virtually eliminated from the control 129, and IFNAR1−/− mice and to a slightly lesser extent in IFNGR−/− mice." (PMID 20386712, 2010). "In order to assess the importance of Nod2 and Rip2 to the downstream IFNα/β-dependent macrophage response, we quantified the induction of RANTES mRNA, which depends on type I IFN secretion and signaling via the IFNαβ receptor (IFNAR1) in this infection model." (PMID 19578435, 2009). "We performed a more detailed characterization of the model using the following parameters: administration of 0.1 mg per mouse of anti-IFNAR1 mAb, followed 48 h later by infection with CHIKV, MAYV, or ONNV at a dose of 105 TCID50." (PMID 41532622, 2026). "Briefly, groups of 7-week-old female C57BL/6 mice received anti-IFNAR1 mAb (ip) one or two days before infection (ip) with doses of MAYV strain MAYV/1954/TT/TC625 (genotype D) ranging from 103 to 105TCID50." (PMID 41532622, 2026). "We further assessed the condition of 0.1 mg anti-IFNAR1/mouse 48 h before infection with 105TCID50 of MAYV in mature adult mice." (PMID 41532622, 2026). "A dose of 1 mg per mouse of anti-IFNAR1 mAb, followed by a viral dose of 104TCID50, elicited death in 83% and 67%, and a symptomatic disease in 100% and 83% of mice when the mAb was administered 48 h or 24 h before infection respectively." (PMID 41532622, 2026). "The results demonstrated that infection of wild-type LSDV but not LSDVΔ122 reduced IFN-β-induced endogenous association between IFNAR1 and IFNAR2." (PMID 41525414, 2026). "C57BL/6 mice were injected intraperitoneally with varying anti-IFNAR1 antibody doses before intraperitoneal infection with CHIKV or MAYV." (PMID 41532622, 2026).
infection (continued). "To further confirm that IFNAR1 controls renal colonization by L. interrogans we employed a second in vivo model utilizing a low dose subcutaneous infection route that more closely resembles physiologic infection." (PMID 41499635, 2026). "We, therefore, infected animals with a high viral dose (105TCID50) and tested three anti-IFNAR1 mAb dosing regimens: 0.1 mg or 1 mg administered 48 h before infection, and 1 mg administered 48 h before infection followed by an additional 0.5 mg dose at 1 dpi to ensure continued blocking of IFNAR1." (PMID 41532622, 2026). "Furthermore, the Type I interferon receptor was blocked with an IFNAR1 antibody, followed by infection with RSV in RAW264.7 cells." (PMID 40245000, 2025). "Therefore, to promote viral dissemination in a pregnant dam, we transiently depleted type I IFN signaling using an IFNAR1-blocking antibody (αIFNAR1) one day prior to infection to acutely permit productive OROV replication and viral dissemination." (PMID 40964022, 2025). "At all doses tested, Ifnar1-/- mice succumbed to lethal infection sooner than Stat1-/- mice." (PMID 40694555, 2025). "Further, we show that mice deficient in the IFNα/β receptor subunit 1 (IFNAR1) or STING had higher bacterial burdens and increased renal colonization following infection in vivo suggesting that cGAS-STING-driven type I IFN is required for the host defense against L. interrogans." (PMID 40501870, 2025). "However, it is worth noting that bacterial survival increased in IFNAR1−/− mice after infection intravenously with L. monocytogenes, indicating that the route of infection affects the effect of type I IFNs." (PMID 40137714, 2025). "Over the course of infection, IFNAR1 and IFNGR1 decreased, whereas IFNAR2 remained stable." (PMID 40558091, 2025). "In this study, four-week-old male and female C57BL/6 IFNAR1−/− mice were successfully infected with WT YFV_HS306/2018, belonging to a new lineage isolated during the 2018 outbreak in Brazil, and they developed disease consistent with infection by YFV." (PMID 41157597, 2025). "Through a comprehensive evaluation of clinical signs, histopathological sections, and viral load quantifications across various tissues and organs, we established an E18 animal infection model employing 2-day-old IFNAR1-KO mice that were intracranially injected with 106 TCID50 of E18." (PMID 40733627, 2025). "Infections with the B/Victoria strain also demonstrated enhanced replication in IFNAR1-KO cells." (PMID 40872812, 2025). "We previously showed that sca2::Tn R. parkeri strains are attenuated in lethality and dissemination from the skin to the liver and spleen following i.d. infection of Ifnar1−/−; Ifngr1−/− DKO mice, and our current results extend these findings to the lung and brain." (PMID 39819005, 2025). "Moreover, IRF1 expression was diminished in Ifnar1–/– pBMDMs following MPXV infection, indicating that IRF1 functions downstream of type I IFN signaling." (PMID 41225161, 2025). "A further comparative analysis of C57 and IFNAR1-KO mice revealed that the infection symptoms, survival rates, and weight fluctuations in the animal models subjected to both injection methods for IFNAR1-KO mice were significantly more favorable than those observed in C57 mice." (PMID 40733627, 2025). "In the same study, infection of moMΦ with Georgia 2007 strain down-regulated other receptors, such as interferon receptors (IFNAR1, IFNAR2, IFNGR) and interleukin receptors (IL4R, IL10RA, IL10RB, and IL17RA), as well as transcriptomic factors (e.g., FOS, JUN, and TBK1)." (PMID 40530033, 2025). "Unlike the decrease in persistent MHV68 lung replication observed in mice lacking STAT1 in B cells, infectious MHV68 levels in the lungs were not altered by the B cell-specific IFNAR1 deficiency at 16 days post-infection." (PMID 39440973, 2024).
infection (continued). "Alternatively, anti-IFNAR1 mAb treatment may help correct a functionally overactive innate immune response, such as that occurring during the chronic stage of LCMV clone 13 infection, where the IFNAR1 blockade improved CD8+ T-cell viral control." (PMID 39535221, 2024). "In the testes, at 7 days post-infection, Zika viral RNA was detected in the Sertoli cells and some spermatogenic cells in the seminiferous tubules, and Leydig cells and testicular macrophages in the interstitium of Ifne-/- and Ifnar1-/- mice." (PMID 39621805, 2024). "Indeed, direct infection of DCs appeared to be a major contributor to priming as specific deletion of IFNAR1 expression from DC1s was sufficient to augment the polyfunctionality of the RRV-specific CD8+ T-cell response." (PMID 39535221, 2024). "Further studies in IFNAR1−/− mice showed that these mice cannot spontaneously control parasite burden in the footpad, draining lymph node and spleen and carry comparable parasite loads in wild type mice over 150 days infection." (PMID 39702382, 2024). "Notably, our infection assay demonstrated that PK-15 Ifnar1 k/o and PK-15 Stat2 k/o cells supported the replication of both IAV and AKAV in the presence of poly (I:C), suggesting that the effect of Ifnar1 k/o is shared by Stat2 k/o." (PMID 37939052, 2023). "IEIs of TLR3-, IRF7-, UNC93B1-, TICAM1-, TBK1-, and interferon alpha and beta receptor subunit 1 (IFNAR1)-dependent type I interferon immunity have been described to underlie life-threatening COVID-19 pneumonia in patients with no prior severe infection." (PMID 37559153, 2023). "Variants in IFNAR1 and IFNAR2 could potentially be new targets for therapies that limit the infection and the resulting inflammation by SARS-CoV-2 infection." (PMID 38003785, 2023). "Additionally, in the context of other arboviruses, Tlr3 has been shown to be both protective and pathologic during West Nile virus (WNV) infections in the brain and is expressed in response to infection in both wild-type and Ifnar1−/− mice." (PMID 37800949, 2023). "To evaluate whether NS4A-E19G contributes to infection of the brain, we s.c. inoculated Ifnar1-/- mice with 103 PFU of NS4A-E19G, ZIKV-IC, or the mouse-adapted virus lineage, VP-C." (PMID 37800949, 2023). "However, the subtype-dependent difference observed in our study offers new insights into the possible roles of IFNAR1 in control and modulation of the infection and replication of different strains of influenza A virus." (PMID 35056582, 2022). "To determine which cell population(s) IFN-β may act on to defend against VACV∆C7L infection, we first analyzed IFNAR1 protein expression in different cell populations from lung." (PMID 35351885, 2022). "Given that lung AECIIs are the major early producers of IFN-β upon intranasal VACV∆C7L infection and highly IFNAR1 expressed, we hypothesized that IFN signaling on lung AECII might be important for restricting VACV∆C7L infection in the lungs." (PMID 35351885, 2022). "Taken together, these results suggest a role for eosinophils and the sustained production of CCL5 in the immune response towards PbA-infection in Ifnar1-/- mice that may contribute to ECM protection." (PMID 34659202, 2021). "In contrast to antibody-mediated blockade of IFNAR1 at the time of infection, which led to significantly worse disease outcomes, IFNAR1 blockade just prior to the resolution phase of acute mucosal infection significantly delayed the progression of genital inflammation." (PMID 34047696, 2021). "(b) Survival of Ifnar1-/-;Ifngr1-/- mice upon i.v. infection with 107R. parkeri." (PMID 34423779, 2021). "However, MA-CCHFV infection was lethal in young-female WT mice and female Ifnar1-/- and Rag1-/- mice demonstrating that resistance to MA-CCHFV by female mice is age-dependent and requires both innate and adaptive host responses." (PMID 33416494, 2021).